MIR550A2 (microRNA 550a-2)
Synonyms: hsa-mir-550-2; hsa-mir-550a-2; MIR550-2; MIRN550-2; mir-550a-2
Gene: MicroRNA gene on chromosome 7 (32,732,981 to 32,733,077, forward strand). Ensembl gene ENSG00000207573.
Gene Ontology:
Biological process: miRNA-mediated post-transcriptional gene silencing
Cellular component: RISC complex